MIR133B (microRNA 133b)
Synonyms: hsa-mir-133b; MIRN133B; miRNA133B; mir-133b
Gene: MicroRNA gene on chromosome 6 (52,148,923 to 52,149,041, forward strand). Ensembl gene ENSG00000199080.
Gene Ontology:
Biological process: miRNA-mediated post-transcriptional gene silencing
Cellular component: RISC complex
Homologues: Orthologues: chimpanzee ptr-mir-133b (100% identical), macaque mml-mir-133b (100% identical), guinea pig MIR133B (90% identical), mouse Mir133b (87% identical), rabbit MIR133B (87% identical), dog MIR133B (71% identical), rat Mir133b (71% identical), pig ssc-mir-133b (66% identical), tropical clawed frog xtr-mir-133b (58% identical), zebrafish mir133b (55% identical), zebrafish dre-mir-133c (49% identical), Drosophila melanogaster mir-133 (44% identical). Paralogues in human: MIR133A2 (55% identical), MIR133A1 (47% identical).
Diseases named in the same sentence as MIR133B in open-access papers:
MIR133B is named in the same sentence as 10 diseases in open-access papers, as found by Europe PMC text mining. Sharing a sentence is not in itself a finding about the gene and the disease. The quoted sentences say what the papers report.
atrial fibrillation (1 paper, 2013). A disorder characterized by an electrocardiographic finding of a supraventricular arrhythmia characterized by the replacement of consistent P waves by rapid oscillations or fibrillatory waves that vary in size, shape and timing and are accompanied by an irregular ventricular response. "We re-sequenced the MIR1-1, MIR1-2, MIR133A1, MIR133A2, and MIR133B genes, that encode the cardiac-enriched miRNAs, miR-1 and miR-133, in 120 individuals with familial atrial fibrillation and identified 10 variants, including a novel 79T > C MIR133A2 substitution." (PMID 23497314, 2013).
cervical carcinoma (1 paper, 2016). A carcinoma arising from either the exocervical squamous epithelium or the endocervical glandular epithelium. "In these abnormal contexts, MIR133b in human cervical carcinoma targets EGFR and FGFR1, similarly acting as a tumor suppressor." (PMID 27471470, 2016).
craniosynostosis (1 paper, 2016). Craniosynostosis is defined as the premature fusion of one or more cranial sutures leading to secondary distortion of skull shape resulting in skull deformities with a variable presentation. "More roles have been ascribed for FGF signaling in craniofacial development, with FGFR1 specifically linked to skeletal dysplasias and craniosynostosis in both humans and mice, suggesting a mechanism by which Mir133b may regulate craniofacial development." (PMID 27471470, 2016).
gastric cancer (1 paper, 2016). A primary or metastatic malignant neoplasm involving the stomach. "In addition, Mir133b is down-regulated in several cancers, including muscle rhabdomyosarcoma, osteosarcoma, and prostate, colorectal and gastric cancers." (PMID 27471470, 2016).
Stroke (1 paper, 2020). Sudden impairment of blood flow to a part of the brain due to occlusion or rupture of an artery to the brain. "In addition, Mir133b may promote neurite outgrowth via targeting RhoA and miR-133b may be critical for neural functional recovery after spinal cord injury and stroke in several organisms." (PMID 32093602, 2020).
thyroid cancer (1 paper, 2019). "Furthermore, MIR133B was found to inhibit PKHD1, which suppresses the proliferation of thyroid cancer cells and promotes the death of cancer cells, but its expression is low in early-stage PTC." (PMID 31126066, 2019).
tumor (3 papers, 2016 to 2020). "As GDNF is downregulated by MIR133B, it inhibits tumor migration and proliferation." (PMID 32211020, 2020). "The expression of SMC2 modified by MIR133B could downregulate the control of tumor proliferation, migration, and apoptosis." (PMID 32211020, 2020). "The most important carcinogenic mechanism and cellular dysfunctions at this stage of CRC are as follows: MIR133B is modified by DNA methylation to downregulate GDNF and SMC2, inhibiting tumor proliferation and migration." (PMID 32211020, 2020). "MIR133b, MIR1247, and MIR1228 expression was not increased in the tumor tissue in comparison to matched adjacent nontumor tissue (cohort 1, n = 29)." (PMID 31879968, 2020).
MIR133B also shares sentences with these, for which no sentence is quoted: cancer (2 papers); osteosarcoma (1); skeletal dysplasia (1).